TNF (tumor necrosis factor)
Diseases named in the same sentence as TNF in open-access papers (continued):
Sharing a sentence is not in itself a finding about the gene and the disease.
breast carcinoma (continued). "Also, human breast cancer survivors who participated in a six month endurance training intervention had significant reductions in serum levels of systemic inflammatory cytokines such as TNF-α and IL-6." (PMID 32542046, 2020). "Finally, this study provides evidence that AIM can act as a TNF-α inhibitor on human breast cancer." (PMID 32455624, 2020). "In this regard, by using global run-on coupled with deep sequencing (GRO-seq) in MCF-7 breast cancer cells, it was demonstrated that TNFα was responsible for exposing latent estrogen receptor binding sites to which estradiol could bind to regulate gene expression." (PMID 32391269, 2020). "In addition, TNFα pretreatment of breast cancer cells protected them from radiation insults." (PMID 32391269, 2020). "Thus, combined high content phenotypic screening, and pathway network analysis identifies an existing serotonin receptor modulator with selective activity upon breast cancer cell cycle and TNF signaling pathways representing a potential drug repurposing opportunity for specific breast cancer types." (PMID 31757681, 2020). "Furthermore, it was found that TNF-α reversed the effects of OA on breast cancer cells." (PMID 31341911, 2019). "Similarly, breast cancer-derived exosomes can induce increases in mRNAs of pro-inflammatory cytokines such as interleukin (IL)-6, tumor necrosis factor (TNF), granulocyte colony stimulating factor (G-CSF) and chemokine CCL2, through a Toll-like receptor (TLR)-2 stimulation and NF-κB in macrophages." (PMID 30895170, 2019). "It has been reported that high levels of IL-6 and TNFα are correlated with strong tumor invasiveness and poor prognosis of breast cancer, and our results show that TNFα induced GM-CSF in cancer cells, suggesting that TNFα may enhance tumor growth through the induction of GM-CSF." (PMID 31581558, 2019). "Hence, neutralisation of TNF as well as TNFR2 by using TNF-antagonist drugs might be an effective therapeutic strategy for breast cancer cells." (PMID 31239840, 2019). "Thus, inactivation of NF-κB signaling may decrease PTX3 expression in breast cancer cells by decreased p-p65/NF-κB and TNF-α." (PMID 30740360, 2019). "For that reason, TNF-α could be used as a prognostic marker in breast cancer." (PMID 31137684, 2019). "However, controversial effects have been attributed to IL-1β and TNF-α in breast cancer." (PMID 31093512, 2019). "In addition to MMP9, BMAL1 also up-regulated the downstream target genes of NF-κB in breast cancer cells, such as TNF, IL8, uPA, and luciferase reporter gene showed that BMAL1 could activate the activity of NF-κB reporter gene." (PMID 31346317, 2019). "Together, the results presented can suggest that boiling histotripsy could be a potential therapeutic approach for not only mechanically destroying solid tumours (e.g., breast cancer) but also promoting immunogenic cell death via TNF-induced necrosis to trigger antitumour immunity." (PMID 31227775, 2019). "However, it remains unknown whether E2 induces TNFα via activation of NF-κB in E2-deprived breast cancer cells." (PMID 29531812, 2018). "However, the effect of TNF on the expression of other ganglioside-specific GT genes in breast cancer cells was still unknown." (PMID 29698439, 2018). "Therefore, combination of TNF-α antibody and chemotherapy may be a successful strategy for treatment of chemo-resistant advanced breast cancer." (PMID 29559745, 2018). "Moreover, the blockade of tumor necrosis factor (TNF)-α reduced CD47 and increased phagocytosis, suggesting that the TNF-NF-κB signaling pathway directly governs CD47, by interacting with a constituent enhancer placed within a CD47-associated SE specific to breast cancer." (PMID 30213113, 2018).
breast carcinoma (continued). "However, curcumin pre-treatment for 5 days in cisplatin-treated rats significantly reduced the levels of TNF-α (p < 0.001), IL-6 (p < 0.01), and IL-8 (p < 0.05) whereas significantly improved the level of IL-10 (p < 0.001) as compared to cisplatin-treated breast cancer rats." (PMID 28420987, 2017). "It was demonstrated recently that in breast cancer, EzH2 promotes a constitutive activation of NF-κB that leads to an increase in its target genes expression, including IL-8, IL-6 and TNF-α cytokines, suggesting that it might be doing the same in our model of CAC." (PMID 29285251, 2017). "Next, we evaluated whether TNF-α could promote the growth of breast cancer through HBXIP." (PMID 28938560, 2017). "Preclinical studies demonstrating important functional roles for the receptor activator of nuclear factor-κB (RANK) pathway, a member of the tumor necrosis factor (TNF) superfamily in breast development suggest that targeting this pathway could have utility in primary breast cancer prevention." (PMID 29088745, 2017). "Furthermore, tumor necrosis factor (TNF)-related apoptosis-inducing ligand expressing recombinant adenovirus regulated by miRNA response elements of miR-122 has shown an obvious advantage in accelerating apoptosis of breast cancer and esophageal cancer." (PMID 28177059, 2017). "Interestingly, we found that the treatment with TNF-α could accelerate the proliferation of breast cancer cells." (PMID 28938560, 2017). "Thus, we conclude that TNF-α promotes the growth of breast cancer through the positive feedback loop of TNFR1/NF-κB (and/or p38)/p-STAT3/HBXIP/TNFR1.Our finding provides new insights into the mechanism by which TNF-α drives oncoprotein HBXIP in the development of breast cancer." (PMID 28938560, 2017). "Moreover, we observed that the mRNA levels of TNF-α were positively correlated with those of HBXIP in above tissues (r = 0.7684, **p< 0.01, Pearson's correlation), raising the possibility that TNF-α may up-regulate HBXIP in breast cancer." (PMID 28938560, 2017). "Although our finding that TNF-α is associated with increased breast cancer risk in premenopausal women is not supported by previous studies, the association could be real since TNF-α has been found to stimulate the enzymes of estrogen synthesis." (PMID 28983080, 2017). "The higher expression of cytokines, tumour necrosis factor alpha (TNF-α), cyclooxygenase-2 (COX-2), and B-cell lymphoma extra large (Bcl-xL) in inflammatory breast carcinoma was found to be associated with increasing tumour grade and the metastatic behavior of breast carcinomas." (PMID 28479926, 2017). "Indeed, survivors of breast cancer frequently show significant cognitive damage, and notably, findings from a study with breast cancer patients showed evidence of TNF-α and IL-6-mediated altered hippocampal volume and verbal memory difficulties following chemotherapy." (PMID 29202842, 2017). "Moreover, the presence of TNF-α-308 was related to vascular invasion in breast cancer." (PMID 29202842, 2017). "Therefore, TNF-α was utilized to induce metastases of breast cancer cell in vitro." (PMID 28774312, 2017). "By instance, a study with breast cancer and non-Hodgkin lymphoma patients evaluated the coadministration of doxorubicin with the anti-oxidant mesna, finding that the combined regimen was able to reduce the levels of chemotherapy-induced TNF-α, TNFR and related cytokines." (PMID 29202842, 2017). "However, the effect of TNF-α on HBXIP in breast cancer remains poorly understood." (PMID 28938560, 2017). "Thus, we conclude that TNF-α-elevated HBXIP is able to up-regulate TNFR1 in breast cancer cells." (PMID 28938560, 2017). "Hence, TNF-α was used to induce the metastatic process of breast cancer cells." (PMID 28774312, 2017). "In addition, we observed that siTNFR1 could significantly induce apoptosis, suggesting that knockdown of TNFR1 can block the effect of TNF-α on promotion of cell proliferation in breast cancer." (PMID 28938560, 2017).
breast carcinoma (continued). "However, whether TGF‐β1 is the solely factor to induce Il‐17rb in breast cancer cells in the TDLNs needs further investigation since other factors such as TNF‐α can also up‐regulate IL‐17RB in primary fibroblast." (PMID 28993429, 2017). "Importantly, when BM-MSCs were TNFα-pretreated they mimicked L-MSCs in their chemokine production profile and in their ability to promote tumorigenesis not only of lymphoma but also melanoma, and breast carcinoma." (PMID 29069870, 2017). "An alternate and converse approach may exploit the presence of TNF in IBC to make this type of breast cancer a suitable candidate for a class of small molecule drugs designed to mimic the function of the second mitochondria-derived activator of caspases (SMAC/Diablo)." (PMID 28607534, 2017). "IL-1β and TNF-α may alter stromal cells enhancing the expression of CCL2, CXCL8, and CCL5 by cancer-associated fibroblast and mesenchymal stem cells in the inflammatory tumor microenvironment of breast cancer." (PMID 27886105, 2016). "Hence, targeting TNF-α should be considered as a therapeutic approach for breast cancer treatment." (PMID 26888313, 2016). "From our results we conclude that TNF-α-induced activation of the MAPK/ERK signaling pathway may promote breast cancer cell migration via both upregulation of MMP9, CD26 and FAP-α and concentration of these proteases, as also MT1-MMP and MMP2, in the lipid rafts." (PMID 27042827, 2016). "Hence, the aim of this study was to evaluate the associations between two common pro-inflammatory cytokine gene polymorphisms namely, IL6-174 (rs1800795 G>C) and TNF-308 (rs1800629 G>A), and chemotherapy-associated cognitive impairment (CACI) among Asian early-stage breast cancer patients." (PMID 27701469, 2016). "The exposure to TNF-α, induced Twist-1 mRNA and protein expression in breast cancer cells, cell lines and mouse models, leading to the hypothesis that there is a signaling axis through which the tumor microenvironment and TNF-α elicit Twist-1 expression to promote cancer metastasis." (PMID 27429011, 2016). "The potent effects of β-nitrostyrene derivatives on inhibiting the TNFα-induced NF-κB survival pathway in a truncated retinoid X receptor α (tRXRα)-dependent manner resulted in a synergistic effect of β-nitrostyrene derivatives and TNFα on inducing breast cancer cell apoptosis." (PMID 27875549, 2016). "Similarly, VDR repression by TNF-α sensitizes breast cancer cells to TGF-β1-induced EMT." (PMID 26880977, 2016). "Interestingly, monocytes from patients with early breast cancer produced similar amounts of cytokines (IL-8, IL-6, IL-1β and TNF) as those observed in patients with advanced disease (LRR/MBC), suggesting that monocytes are functionally affected already early in the disease." (PMID 25992611, 2015). "In some cancers including multiple myeloma, breast cancer, prostate cancer, and renal carcinoma hypercalcemia may be induced by production of osteoclast-activating factors such as tumor necrosis factor alpha, interleukine 6, and receptor activator of nuclear factor-κB ligand (RANKL)." (PMID 26499069, 2015). "Here, we identified the impact of TNF-α and IL-1β on the inflammatory phenotype of CAFs and MSCs by determining the expression of inflammatory chemokines that are well-characterized as pro-tumorigenic in breast cancer: CCL2 (MCP-1), CXCL8 (IL-8) and CCL5 (RANTES)." (PMID 25928089, 2015). "The inflammatory mediators, TNFα and IL-6, which are associated with insulin resistance in T2DM, enhanced estrogen production in both normal and breast cancer cells and could be expected to result in the development and proliferation of breast cancer cells." (PMID 25866823, 2015). "Furthermore, we previously identified that HIF-1α could directly inhibit VASP transcription during the TNF-α-induced metastasis and adhesion of breast cancer MCF-7 cells." (PMID 25051011, 2014).
breast carcinoma (continued). "The strong metastasizing activities resulting out of the cooperation between hyper-activated Ras and TNFα suggest that the activation of WT-Ras by TNFα may give rise to more aggressive disease in breast cancer patients expressing WT-Ras and high levels of TNFα." (PMID 24598028, 2014). "Similarly, both TNFα and interleukin-1β (IL-1β) are expressed at low levels in normal breast epithelial cells, but are upregulated in the majority of breast cancer patients, with pronounced expression of both cytokines in over 80% of patients who experience breast tumor relapse." (PMID 25566498, 2014). "Only four combinations of TNF c.-418 and c.-488 were analyzed due to the absence of other combinations in the study participants and two of them showed a significant association with breast cancer risk." (PMID 25559835, 2014). "To investigate whether TNF-α sensitized breast cancer cells to WA or Cel by enhancing the inhibition of cellular proteasome activities, we studied the cellular proteasomal CT-like activity and accumulation of ubiquitinated proteins and the proteasome target protein, IκBα." (PMID 25419573, 2014). "Taken together, these results suggest that TNF-α could sensitize breast cancer cells MDA-MB-231 to WA and Cel, at least in part, through inhibiting the activation of NF-κB signaling, leading to XIAP inhibition with subsequent upregulation of caspase-3 and -9 activities." (PMID 25419573, 2014). "While having cytotoxic effects when acutely administered to tumors, the chronic presence of TNFα in breast tumor sites leads to increased tumor aggressiveness; IL-1β up-regulates processes that contribute to higher angiogenesis, tumor growth and progression in breast cancer." (PMID 24598028, 2014). "Data revealed that breast cancer subjects had significantly higher systolic blood pressure (p = 0.03), glucose (p = 0.01), triglycerides (p = 0.001), leptin (p = 0.044), resistin (p = 0.04), Ang II (p = 0.02), TNF-α (p = 0.045), and CRP (p = 0.04) than controls." (PMID 23374911, 2013). "Thus, an inhibition of IκB/NF-κB phosphorylation by KSG-002 may result in a reduction of TNFα production from TAMs, suppressing breast cancer growth and metastasis." (PMID 23818931, 2013). "Hence, we further examined whether KSG-002 affects macrophagic TNFα-induced breast cancer cell migration." (PMID 23818931, 2013). "This is cliniclaly relevant since the TNF-induced angiogenesis inhibitor thalidomide is used for treatment of cancers, and since the TNF-induced activation of NF-κB transcripional programs that occurs in breast cancer and cultured endothelial cells appear very similar." (PMID 23281897, 2012). "Additionally, several studies also found that TNF-α-308 G/A and another SNP in the promoter of TNF-α (-1031C>T, rs1799964) were significantly associated with prognosis of bladder cancer and breast cancer, clinical characteristics of colorectal cancer, and severity of lung cancer." (PMID 21995493, 2011). "To characterize the role of CD44v4 in mediating breast cancer cell transendothelial migration, we next examined the effects of CD44v4 knockdown as well as removal of tumor cell surface sLex moieties on tumor cell adhesion to and migration across TNF-α pre-activated HUVEC monolayers." (PMID 18350162, 2008). "Furthermore, this p21 location has been related to breast cancer resistance to the TNF-α apoptotic effect, and it could be explained by the IFNγ effects mediated by TNFRI." (PMID 17697357, 2007). "Moreover, TNF-α levels were increased before treatment in our breast cancer patients when compared to normal controls, and even with their reduction after treatment with either paclitaxel or docetaxel, never returned to the levels observed in the healthy control group." (PMID 12085250, 2002). "To investigate the role of macrophage-derived EVs in endocrine resistance, we isolated EVs from TNF-α-conditioned macrophages (TNF EVs) and treated MCF-7 ER+ breast cancer cells with these vesicles." (PMID 40567500, 2025).
breast carcinoma (continued). "Dual-treatment with TGF-β1 and TNF-α induces EMT signatures in premalignant M2 cells, which are part of the MCF10A breast cancer progression model." (PMID 40833805, 2025). "TNF and VEGFA are more commonly seen in studies of drugs that promote and inhibit sex hormone secretion, and EGFR inhibits gonadal axis secretion in breast cancer patients." (PMID 40238841, 2025). "In this study, we investigated its effects on breast cancer by evaluating PCNA and TNF-α expression and analyzing their molecular and immunological associations using in silico approaches." (PMID 40430573, 2025). "TNF-α and IL-6 promote inflammation in the TME, facilitating breast cancer cell proliferation and metastasis." (PMID 41289612, 2025). "In this study, we first focused on isolating and characterizing EVs derived from both TNF-α conditioned macrophages (TNF EVs) and MCF-7 breast cancer cells (MCF-7 EVs)." (PMID 40567500, 2025). "In postmenopausal women with early breast cancer, longitudinal studies reported short-term increases of 15–48% in IL-6, IL-8, IFN-γ, TNF-α, and IL-10 after adjuvant chemotherapy, returning toward baseline within 6–12 months." (PMID 41153842, 2025). "We found that TNFα does indeed affect the regulation of VGSCs and Na,K-ATPase in MDA-MB-231 breast cancer cells at the levels of RNA expression, protein localization, and protein expression." (PMID 41516295, 2025). "Overall, skimmianine’s dual targeting of PCNA and TNF-α modulates the immune TME, highlighting its potential as a regulator of immune dynamics in breast cancer by simultaneously reversing immune suppression and mitigating tumor-promoting inflammation." (PMID 40430573, 2025). "Several human studies also support this inflammation–angiogenesis axis, reporting positive correlations between IL-6 or TNF-α and circulating VEGF levels in patients with breast cancer, small cell lung cancer, and melanoma." (PMID 41583457, 2025). "Otherwise, in the case of TNFα and CXCL9, mice with control breast carcinoma tumors exhibited increased levels of these cytokines than melanoma-bearing mice." (PMID 39857957, 2025). "Various cytokines released by breast cancer cells (RANKL, IL-1, TNF-α, and M-CSF) directly stimulate the activation of osteoclast." (PMID 40444046, 2025). "For instance, p62 knockdown in breast cancer enhances infiltration of cytotoxic CD8+ T cells and increases pro-inflammatory Th1 cytokines such as IFN-γ, TNF-α, and IL-12." (PMID 41291343, 2025). "In particular, chemotherapy induced the secretion of TNFα by ECs, increasing the production of CXCL1/2 by breast cancer cells." (PMID 39863855, 2025). "Bruni S found that MUC4 expression, induced by TNF-α, hinders the effectiveness of trastuzumab in treating HER2-positive breast cancer by promoting immune evasion." (PMID 40303301, 2025). "Studies have shown that SLUG increases cytoplasmic β-catenin stability by inducing certain inflammatory factors such as IL-8 and TNF-α, while TWIST1 regulates CD24 expression, promoting stem cell characteristics in breast cancer." (PMID 39858015, 2025). "To confirm the results obtained from A549 cells, we used the following cell lines: human breast cancer MCF-7 cells and human fibrosarcoma HT-1080 cells, both of which respond to TNF-α by inducing the activation of NF-κB." (PMID 41302385, 2025). "AE directly modulates the inflammatory milieu by reducing the levels of key pro-inflammatory cytokines such as TNF-α, IL-6, and CRP, as evidenced in breast cancer studies." (PMID 41480347, 2025). "Pro‐inflammatory cytokines such as IL‐1β and TNF‐α further amplify this effect by stimulating both NF‐κB signaling, and ABCG2 expression in certain breast cancer cell lines, suggesting a coordinated response involved in drug resistance." (PMID 40654246, 2025).